GCKR (glucokinase regulator)
Diseases named in the same sentence as GCKR in open-access papers (continued):
Sharing a sentence is not in itself a finding about the gene and the disease.
Insulin resistance (33 papers, 2011 to 2025). Increased resistance towards insulin, that is, diminished effectiveness of insulin in reducing blood glucose levels. "Their findings revealed that the T allele of the GCKR rs780094 variant is associated with lower levels of fasting glucose and insulin resistance and is correlated with higher levels of plasma TGs." (PMID 38918799, 2024). "Our findings suggest that GCKR regulates follistatin secretion and that elevated circulating follistatin associates with an increased risk of T2D by inducing adipose tissue insulin resistance." (PMID 34759311, 2021). "All GLs and GPLs, which were positively associated with GCKR rs780094-T, were associated with an increase in insulin resistance, BMI and ALT, except for 1-stearoyl-GPE (18:0) and 1-palmitoyl-GPE (16:0) which are lysophoshatidylethanolamines." (PMID 31308433, 2019). "The 12Pro allele of PPARG rs1801282 has opposite effects on insulin resistance and BMI in Caucasian subjects, whereas GCKR rs780094 has opposite effects on insulin resistance and lipid levels." (PMID 23101478, 2012). "Notably, a single mutant genetic variant rs1260326 in the glucokinase regulatory protein gene GCKR is implicated in the stress index of insulin resistance." (PMID 36627697, 2023). "Notably, the effect of GCKR polymorphism, in synergy with insulin resistance and T2D, in promoting the onset and progression of NAFLD has been increasingly recognized." (PMID 37711901, 2023). "Additionally, the GCKR rs780094 SNP has been linked to predisposition to insulin resistance in Danish and Japanese populations." (PMID 28225792, 2017). "They found that the risk loci could be subdivided into five clusters including one cluster with four loci, PPARγ, KLF14, IRS1 and GCKR, associated with insulin resistance." (PMID 27312935, 2016). "Previous studies have shown that variants in GCKR may have pleiotropic effects of increasing TG and decreasing insulin resistance." (PMID 26020539, 2015). "There were significant associations between two GCKR variants and insulin resistance for children." (PMID 23383164, 2013). "Our findings support the hypothesis that the GCKR rs1260326-P446L polymorphism influences insulin resistance by interacting with plasma n-3 PUFA levels in MetS patients." (PMID 21674002, 2011). "The Glucokinase regulator (GCKR) (rs1260326) variant, which enhances hepatic lipogenesis via altered glucose metabolism, contributes to hepatic fat accumulation and may indirectly influence renal function through insulin resistance." (PMID 41007724, 2025). "Polymorphisms at the GCKR gene region were firstly identified to be associated with triglycerides levels by genome wide association studies, and the alleles which increasing triglycerides levels were found to lower the glucose, insulin levels and insulin resistance by different association studies." (PMID 23383164, 2013). "Their population-based phenotypic analysis predicted that GCKR rs1260326 (C>T) serves as a key genetic factor for NASH under insulin resistance conditions." (PMID 37711901, 2023). "Two common GCKR variants (rs1260326 and rs780094) have opposing effects in T2D and NAFLD: while they are associated with decreased levels of insulin resistance and a reduced risk of T2D, they increase the level of plasma triglycerides and the risk of NAFLD." (PMID 37711901, 2023). "First, we investigated the association between cognitive aging and three insulin resistance-related genes, namely the ADAMTS9, GCKR, and PPARG genes." (PMID 28225792, 2017). "The G allele of rs780094 in GCKR was associated with increased fasting plasma glucose and HOMA-IR (assessment for insulin resistance)." (PMID 26252223, 2015). "Other genes involved in triggering insulin resistance have been discovered: glucokinase regulatory protein (GKRP), and insulin-like growth factor-I (IGF-I)." (PMID 25566188, 2014).
Insulin resistance (continued). "Triglycerides-increasing alleles of GCKR variants reduce insulin and HOMA-IR index, and protect from insulin resistance in children." (PMID 23383164, 2013). "We firstly observed that the GCKR variants of increasing triglycerides had lower the levels of insulin and HOMA-IR index, and reduce the risk of insulin resistance for Chinese children." (PMID 23383164, 2013). "The triglycerides-increasing alleles of GCKR variants can reduce blood insulin and HOMA-IR index, and the risk of insulin resistance in Chinese children." (PMID 23383164, 2013). "Our data firstly find that the triglycerides-increasing alleles of GCKR variants rs1260326 and rs1260333 lowered insulin and HOMA-IR, and reduced the risk of insulin resistance in Chinese descent children." (PMID 23383164, 2013). "We have demonstrated a significant interaction between the GCKR rs1260326-P446L polymorphism and plasma n-3 PUFA levels modulating insulin resistance and inflammatory markers in MetS subjects." (PMID 21674002, 2011). "The GCKR rs1260326-P446L SNP interacted with plasma n-3 PUFA to influence insulin resistance, suggesting the potential sensitivity of this SNP to dietary factors." (PMID 21674002, 2011). "The study showed that the GCKR rs780094 significantly interacted with insulin resistance, increasing the susceptibility of nondiabetic individuals to NAFLD." (PMID 37711901, 2023). "Similarly, the genetic polymorphisms in different genes such as CAMK2, IGF1, IRS1, GCKR, PPARG, GCK1, and KCTD1 are found associated with insulin resistance and T2DM." (PMID 37829557, 2023). "Moreover, TG-increasing alleles of GCKR variants rs1260326 and rs1260333 lowered insulin and HOMA-IR and reduced the risk of insulin resistance in Chinese." (PMID 31910446, 2020). "Candidate gene and GWAS have identified genetic variants associated with insulin resistance in the non-gravid state, including variants in GCKR." (PMID 32556615, 2020). "Our results suggested GCKR has an effect on development of insulin resistance in Chinese children." (PMID 23383164, 2013). "Homeostasis model assessment of insulin resistance (HOMA-IR), HOMA-B, plasma concentrations of C-peptide, CRP, fatty acid composition and the GCKR rs1260326-P446L polymorphism, were determined in a cross-sectional analysis of 379 subjects with MetS participating in the LIPGENE dietary cohort." (PMID 21674002, 2011). "In conclusion, our results support the notion that n-3 PUFA may play a contributing role in triggering insulin resistance and serum levels of CRP by interacting with a genetic variant at GCKR gene locus." (PMID 21674002, 2011). "Additionally, n-3 polyunsaturated fatty acids (PUFA) may play a contributing role in triggering insulin resistance and serum levels of CRP by interacting with a rs1260326-P446L genetic variant at GCKR." (PMID 38918799, 2024). "GCKR rs1260326 (minor allele: T) may prevent fibrosis in the nondiabetic state, but increases disease severity in the diabetic state, promoting NAFLD histological progression by affecting triglyceride levels, insulin resistance, DNL and mitochondrial function." (PMID 37711901, 2023). "Interestingly, GCKR(TT) was associated with an increased risk of NAFLD in the presence of insulin resistance but a decreased risk in the absence of insulin resistance." (PMID 36875751, 2023). "Thus, we hypothesized that insulin resistance-associated genes, namely the ADAMTS9, GCKR, and PPARG genes, may be linked with cognitive aging." (PMID 28225792, 2017). "Whether or not the GCKR variants associate with insulin resistance in Chinese adults, it needs larger-sample population to verify." (PMID 23383164, 2013). "We genotyped two GCKR variants rs1260326 and rs1260333 in children and adults, and analyzed the association between two variants and triglycerides, glucose, insulin and HOMA-IR using linear regression model, and estimated the effect on insulin resistance using logistic regression model." (PMID 23383164, 2013).
Insulin resistance (continued). "Based on these results we may speculate that n-3 PUFA fatty acids interact with the GCKR gene to influence insulin resistance and this is particularly noteworthy as insulin resistance is believed to be an important factor linking metabolic abnormalities in patients with the MetS." (PMID 21674002, 2011). "Emerging evidence supports genetic determinants of FLD (eg PNPLA3, TM6SF2, MBOAT7, GCKR, HSD17B13) as determinants of insulin resistance and T2D." (PMID 33102799, 2020). "Among the genes involved in the development of insulin resistance are the ADAM metallopeptidase with thrombospondin type 1 motif 9 (ADAMTS9), glucokinase regulator (GCKR), and peroxisome proliferator activated receptor gamma (PPARG) genes." (PMID 28225792, 2017). "The genetic variants related to T2DM in Caucasians are mainly related to insulin resistance, but those in Asians, including Chinese, Japanese, and Koreans, are involved in insulin secretion (GLP1R, PAX4, HNF4A, SLC30A8, HHEX, CDKAL1, CDKN2A/B, and GCKR)." (PMID 35956399, 2022). "Based on our findings, this phenomenon may now be explained by the fact that the GCKR-GCK disruptor may have increased liver cell follistatin secretion, which in turn, may have promoted adipose tissue insulin resistance and an increase of triglyceride levels." (PMID 34759311, 2021). "Besides IRS1 rs2943634 the group of insulin resistance SNPs consisted of PPARG rs1801282, GCKR rs780094, GCKrs1799884, and IGF1rs35767." (PMID 23101478, 2012). "These genes include Patatin-like phospholipase domain containing 3 (PNPLA3), glucokinase regulatory protein (GCKR), and transmembrane 6 superfamily member 2 (TM6SF2), and are independent of insulin resistance." (PMID 37299398, 2023).
Hepatic steatosis (31 papers, 2013 to 2026). Steatosis is a term used to denote lipid accumulation within hepatocytes. "Coding variants in GCKR, the gene encoding GKRP, strongly associate with fatty liver disease, hypertriglyceridemia, and hypercholesterolemia." (PMID 41993393, 2026). "Polymorphisms in genes such as PNPLA3, TM6SF2, and GCKR promote steatosis through interaction with distinct metabolic mechanisms, predisposing to metabolic dysfunction-associated fatty liver disease." (PMID 38626012, 2024). "GCKR rs780094 can also cause hepatic steatosis, impair mitochondrial β-oxidation and cause a predisposition to fatty liver-related liver disease." (PMID 37760857, 2023). "A genome-wide association study (GWAS) in Malaysia has reported a significant association of the GCKR rs1260326 with the development of hepatic steatosis, NAFLD, and nonalcoholic steatohepatitis (NASH)." (PMID 37829557, 2023). "Another GWAS analyzing patients with hepatic steatosis, who had been diagnosed by CT imaging, revealed the association of a glucokinase regulator (GCKR) genetic variant (rs1260326, C > T) with hepatic steatosis." (PMID 34208839, 2021). "Five fatty liver disease-associated SNPs (rs780094 (GCKR), rs2281135 (PNPLA3), rs8418 (PNPLA3), rs58542926 (TM6SF2), rs2980875 (TRIB1)) passed the significance threshold of <0.05 and were directionally consistent with previous studies." (PMID 30978214, 2019). "In fact, in our cohort the rs58542926 T allele (MAF ~ 7%) displayed a 2.5-fold risk of hepatic steatosis higher than the 1.9 fold risk associated to GCKR T allele (MAF ~ 42%)." (PMID 29487372, 2018). "List of common GCKR variants associated with hepatic steatosis, NASH and fibrosis." (PMID 37711901, 2023). "In summary, the phenotypic effects of GCKR gene mutations can be amplified by the interaction of genetic and metabolism factors, positioning the GCKR gene as a key mediator linking metabolic damage to inflammation and fibrosis in fatty liver disease." (PMID 37711901, 2023). "It was found that a variety of gene sites are related to the risk, disease severity, hepatic steatosis and advanced fibrosis of NAFLD, including PNPLA3, TM6SF2, GCKR, MBOAT7, APOC3, HSD17B13, etc.." (PMID 36973654, 2023). "One of the most reported GCKR variants is the rs780094, and the minor T-allele increases the risk of having NAFLD and hepatic steatosis." (PMID 36672614, 2022). "In a study to determine the causal relationship between steatosis and the development of liver damage, a PRS model was developed based on the risk alleles of four genes (PNPLA3, TM6SF2, GCKR, and MBOAT7) that were associated with hepatic steatosis." (PMID 36672614, 2022). "GCKR and PNPLA3 act together to convey susceptibility to fatty liver in obese young adults." (PMID 40507973, 2025). "This is supported by the lack of association of HbA1c with liver steatosis when we restricted our analyses to only glycemia-related instruments and is more consistent with the glucose analyses without GCKR variant." (PMID 38926684, 2024). "Genetic variants in “glucokinase regulatory protein” (GCKR) gene, “solute carrier family 2-member 1” (SLC2A1) gene, and “17-beta hydroxysteroid dehydrogenase 13” (HSD17B13) gene, have also been identified in patients with fatty liver disease." (PMID 36976456, 2023). "Moreover, both GCKR-P446L and PNPLA3-I148M variants have synergistic effects on the NAFLD risk, particularly on hepatic steatosis." (PMID 36672614, 2022). "Notably, GCKR mRNA expression is significantly reduced in patients with severe hepatic steatosis compared to those with mild steatosis, highlighting the need for further research to identify pathogenic GCKR variants and elucidate their role in NAFLD pathogenesis." (PMID 41150798, 2025). "Major genetic determinants of hepatic steatosis in the population include PNPLA3 I148M, TM6SF2 E167K and GCKR P446L." (PMID 30355853, 2018).
Hepatic steatosis (continued). "Genetic variations (PNPLA3, TM6SF2, GCKR, MBOAT7, MERTK, and HSD17B13) are one of the non-modifiable risk factors for metabolic dysfunction-associated fatty liver disease (MAFLD) and MASLD." (PMID 40507973, 2025). "Therefore, an impaired cross-talk of GCKR and GCK along with elevated insulin and glucose levels promotes the DNL and subsequent hepatic steatosis, which leads to another metabolic condition called NAFLD." (PMID 37829557, 2023).
liver disease (20 papers, 2012 to 2026). "Our findings confirm the role of the GCKR variant in the genetic susceptibility to liver disease." (PMID 32443539, 2020). "Given the fact that variants of GCKR have been associated with liver diseases the associations of these variants with lipids, including glycerolipids (GLs), glycerophospholipids (GPLs) and sphingolipids could be of great interest." (PMID 31308433, 2019). "We replicated previous GWAS results, reporting a significant association of TSLP and RORA gene variants with asthma and GCKR, PNPLA3, TRIB1 and TM6SF2 gene variants with the risk of developing liver diseases, notably NAFLD/NASH." (PMID 30978214, 2019). "The steatogenic alleles in PNPLA3, TM6SF2, GCKR and MBOAT7 all associated with increased risk of ICD‐defined ‘other diseases of liver’ (K76), which includes NAFLD (n = 408 455, P = 0.0075–2 × 10−12)." (PMID 29280273, 2018). "In summary, our case-control and meta-analysis demonstrates that the frequency of the GCKR rs780094-T allele is significantly increased in NAFLD cases compared with controls, as well as stratified analysis by ethnicity, liver disease, source of control, NAFLD assessment, age, and obese status." (PMID 30646922, 2019). "CONCLUSIONS: Genetic variation in GCKR and FGF21, together with altered hepatokine signaling, contributes substantially to metabolic dysregulation and liver disease severity." (PMID 41975319, 2026). "Genes of inflammation and immunity (CD276, CDH6, GCKR, HNF1A, HPR, ITGA1, RORA, and STAT4) have been shown to be expressed in liver disease patients." (PMID 22530132, 2012). "None of the polymorphisms of TM6SF2, MBOAT7, GCKR, nor the PRS, were associated with increased risk of development of severe liver disease in the full cohort." (PMID 36166317, 2022).
hypertriglyceridemia (19 papers, 2010 to 2026). A laboratory test result indicating elevated triglyceride concentration in the blood. "Hyperlipidemia, especially hypertriglyceridemia, is strongly associated with GCKR variants according to current studies." (PMID 41150798, 2025). "Johansen identified rare GCKR variants in 438 individuals with hypertriglyceridemia compared with the control cohort." (PMID 41150798, 2025). "According to the literature, the GCKR allele T is linked to an increased response to fenofibrate medication in individuals with hypertriglyceridemia." (PMID 37686209, 2023). "By contrast, in two South Asian population-specific, functionally disruptive, rare GCKR non-synonymous mutations, rs774930016 (p.Ser105Asn) and rs55537970 (p.Arg553Trp), significantly increased risks of hypertriglyceridemia have been reported." (PMID 35328045, 2022). "In this sense, Single Nucleotide Polymorphisms (SNPs) variants of GCKR has been associated by Genome-wide Association Study (GWAS) to hypertriglyceridemia in humans." (PMID 30983961, 2019). "Our results demonstrated a modest association between GCKR variants with in vitro dysfunction and hypertriglyceridemia." (PMID 24879641, 2014). "The finding that rare variants in genes including GCKR are strongly enriched in the cases of hypertriglyceridemia suggests that these variants are collectively relevant to the hypertriglyceridemia phenotype." (PMID 24879641, 2014). "When this analysis was repeated using in silico prediction as a variant classifier, only PolyPhen-2 predicted that deleterious GCKR variants were associated with hypertriglyceridemia." (PMID 24879641, 2014). "Individuals with in vitro deleterious GCKR variants were observed at higher frequency in hypertriglyceridemia cases compared with controls (4.1 versus 1.2%, P = 0.03, two-tailed Fisher's exact test)." (PMID 24879641, 2014). "Genome wide association studies revealed an association between SNP rs780094 of GCKR gene and hypertriglyceridemia in subjects with T2DM." (PMID 21114848, 2010). "shows the relative risk of hypertriglyceridemia for variants rs780094 and rs1260326 at GCKR gene calculated by the multiple logistic regression analysis models." (PMID 21114848, 2010). "Consequently, the clinical utility of testing rare GCKR variants in hypertriglyceridemia remains limited until more robust variant-specific evidence is available." (PMID 41150798, 2025). "However, variant rs146175795 in GCKR is presented in ClinVar with conflicting interpretations of pathogenicity, including one associated with hypertriglyceridemia in two heterozygous individuals." (PMID 37065472, 2023). "In addition to the rs1260326, functionally deleterious, rare GCKR exonic mutations detected by biochemical and cellular biological assays were collectively associated with hypertriglyceridemia." (PMID 35328045, 2022). "Additionally, when considering only GCKR missense variants—those for which accurate in silico predictions are most necessary—the association between PolyPhen-2 predictions and hypertriglyceridemia was weakened (P = 0.14)." (PMID 24879641, 2014). "Moreover, rare variants in GCKR have been shown to be associated with serum triacylglycerol and cholesterol levels in healthy adults and to be overrepresented in individuals with hypertriglyceridaemia." (PMID 24568320, 2014). "Additionally, rare non-synonymous GCKR variants collectively have been shown to affect triglyceride levels, and also appear enriched in hypertriglyceridemia." (PMID 24879641, 2014). "Notably, functional results often did not agree with computational prediction algorithms; the use of in silico predictions alone would have resulted in a dramatically different interpretation of the role of GCKR variants in hypertriglyceridemia." (PMID 24879641, 2014).